VWF (von Willebrand factor)
Diseases named in the same sentence as VWF in open-access papers (continued):
Sharing a sentence is not in itself a finding about the gene and the disease.
Von Willebrand disease (continued). "Deficiency or/and abnormality of von Willebrand factor (VWF) leads to von Willebrand disease (VWD), which is the most common inherited bleeding disorder." (PMID 33776566, 2021). "von Willebrand Disease (vWD) is usually autosomal dominant and results from mutations in the von Willebrand factor gene." (PMID 34394804, 2021). "Von Willebrand’s disease is a rare, inherited bleeding disorder characterized by defective platelet adhesion and subsequent coagulation defect caused by mutations in the VWF gene." (PMID 33920939, 2021). "Qualitative or quantitative deficiency of plasma VWF multimers causes a bleeding disorder called von Willebrand disease." (PMID 34904569, 2021). "FVIII and (active) VWF both play a central role in hemostasis, illustrated by the severe bleeding phenotype associated with hemophilia A and von Willebrand disease, respectively." (PMID 32250570, 2020). "The high importance of VWF for balanced hemostasis is conveyed by the appearance of bleeding disorders such as the von Willebrand disease caused by an inherited quantitative or functional VWF deficiency." (PMID 33015097, 2020). "von Willebrand disease (VWD) is the most common inherited bleeding disorder caused by defective or deficient von Willebrand factor (VWF)." (PMID 31793247, 2020). "With regard to vWF, a number of studies in vWF-deficient animals and in patients suffering from Von Willebrand disease have been performed." (PMID 31824501, 2019). "This premature clearance of FVIII is caused by a lower affinity of the FVIII:VWF complex and leads to the bleeding disorders hemophilia A and von Willebrand disease (VWD)." (PMID 31349985, 2019). "VWF is of high importance for a balanced hemostasis, since quantitative or functional VWF deficiency causes von Willebrand disease, a common inherited bleeding disorder." (PMID 30972039, 2019). "Mutations that alter the normal size distribution of VWF and result in reduction of large multimers can hence lead to the subtype 2A of von Willebrand Disease (VWD), the most common hereditary bleeding disorder." (PMID 30645640, 2019). "Mutations in VWF that impair multimerization can lead to subtype 2A of the bleeding disorder von Willebrand Disease (VWD)." (PMID 30645640, 2019). "Two of the methionine residues are located in an area of the A1 domain where congenital mutations are commonly found that are associated with type 2B von Willebrand disease, a bleeding disorder where VWF binds strongly to platelets clearing them from plasma." (PMID 30222754, 2018). "The activity of vWF was normal (155%), but further analysis using gel electrophoresis revealed loss of large vWF multimers, which was a typical finding of acquired type 2A von Willebrand disease." (PMID 28789675, 2017). "Von Willebrand disease (VWD) is a common human bleeding disorder characterized by a defect of coagulation caused either by low plasma levels of von Willebrand factor (VWF) or a dysfunctional VWF." (PMID 28806915, 2017). "These mutations occur in type 2B von Willebrand disease, which is associated with thrombocytopenia, loss of plasma VWF multimers and bleeding due to VWF-mediated platelet agglutination." (PMID 28497779, 2017). "Higher vWF levels increase the risk for thrombosis and embolism whereas deficiency in vWF activity leads to the human bleeding disorder von Willebrand's disease." (PMID 28348515, 2017). "In von Willebrand disease, mutations in VWF can perturb formation of WPBs and affect the release of VWF and the string formation, leading to excessive bleeding, thus correct biogenesis of WPBs and storage of VWF is crucial for normal haemostasis." (PMID 27068535, 2016). "von Willebrand disease (VWD)-type 2B is characterized by gain-of-function mutations in the von Willebrand factor (VWF) A1-domain, leading to increased affinity for its platelet-receptor, glycoprotein Ibα." (PMID 27212476, 2016).
Von Willebrand disease (continued). "VWF is particularly well known due to its importance in hemostasis, illustrated with the functional deficiency of vWF known as von Willebrand disease (VWD), a well-characterized and common collection of bleeding disorders." (PMID 27025194, 2016). "We identified three novel mutations (p.Gly39Arg, p.Lys157Glu, p.Cys379Gly) and one previously known mutation (p.Asp141Asn) in the von Willebrand factor propeptide from three von Willebrand disease patients." (PMID 26088471, 2015). "Type 1 von Willebrand disease is a highly heterogeneous bleeding disorder that is characterised by a partial quantitative deficiency of functionally normal von Willebrand factor (VWF)." (PMID 26630678, 2015). "With respect to the VWF variant, we considered her to be affected with autosomal dominant von Willebrand disease." (PMID 24954083, 2014). "For example, it has already been shown that self-association of VWF can result in acquired von Willebrand Disease in devices, including ventricular assist devices, a blood disorder that can be amplified by shear-induced receptor shedding in platelets." (PMID 25171175, 2014). "Both have been studied for many years and causal genes (UGT1A1 for Gilbert's syndrome and VWF for von Willebrand disease) are known." (PMID 25188385, 2014). "Von-Willebrand disease (VWD) is one of the platelet dysfunction disorders that results from a deficiency of Von-Willebrand factor, which is essential for hemostasis." (PMID 25243089, 2014). "High levels of VWF are associated with thrombosis, while low VWF levels are associated with an increased risk of bleeding and the diagnosis of von Willebrand Disease (VWD)." (PMID 25409031, 2014). "An inherited bleeding disorder known as von Willebrand disease (VWD) is associated with an abnormality in VWF, and type 1 VWD is the commonest form that is associated with low VWF : Ag." (PMID 25759835, 2014). "In our study, we used Haemate HS (vWF activity 2200IE), which is clinically used as vWF substitute in vWF deficiencies (von Willebrand diseases)." (PMID 24705415, 2014). "VWF was first identified in hereditary bleeding disorder known as von Willebrand disease (VWD) and later it has been associated with other clinical conditions such as cancers, clotting, and vascular and liver disorders." (PMID 25759835, 2014). "Meanwhile, in platelet-type von Willebrand disease, mutations of GPIb functional receptors can compromise haemostasis by increasing the affinity for vWF." (PMID 24982253, 2014). "Deficiency or dysfunction of VWF causes von Willebrand disease (VWD), the most common genetic bleeding disorder in man." (PMID 24106610, 2013). "Type 2B von Willebrand disease was first described in 1980 and is caused by a functionally defective von Willebrand factor (VWF)." (PMID 23327637, 2013). "Von Willebrand disease (VWD) is the most common hereditary coagulopathy which results from the deficiency or abnormal function of von Willebrand factor (VWF) which is required for platelet adhesion and aggregation." (PMID 23327637, 2013). "Pseudo (platelet-type)-von Willebrand disease is a rare autosomal dominant bleeding disorder caused by an abnormal function of the glycoprotein lb protein; the receptor for von Willebrand factor." (PMID 23327637, 2013). "von Willebrand disease (vWD) is an autosomal hereditary bleeding disorder associated with a quantitative or qualitative defect of von Willebrand factor (vWF)." (PMID 24385752, 2013). "Low VWF levels are a diagnostic criterion for Von Willebrand Disease (VWD), the most common inherited bleeding disorder." (PMID 22792389, 2012). "von Willebrand disease (VWD) is the most common inherited bleeding disorder caused by mutations in the VWF gene, which result in quantitative and/or qualitative defects in VWF." (PMID 22479377, 2012). "Von Willebrand disease (VWD) is an autosomal recessive congenital bleeding disorder with deficiency or dysfunction of von Willebrand factor (VWF)." (PMID 24575258, 2012).
Von Willebrand disease (continued). "Quantitative and/or qualitative deficiency of von Willebrand factor (vWF) is associated with the most common inherited bleeding disease von Willebrand disease (vWD)." (PMID 24385719, 2012). "One of the central components of coagulation is von Willebrand factor (VWF), deficiencies of which are the basis for the bleeding disorder von Willebrand disease (VWD)." (PMID 23049555, 2012). "The central role of the GPIbα-VWF interaction in mediating initial platelet adhesion is illustrated by the bleeding disorders Bernard Soulier syndrome and von Willebrand disease, caused by deficiency of GPIb-IX-V or VWF respectively." (PMID 21914206, 2011). "Use of animal models of inherited and induced von Willebrand factor (VWF) deficiency continues to advance the knowledge of VWF-related diseases: von Willebrand disease (VWD), thrombotic thrombocytopenic purpura (TTP), and coronary artery thrombosis." (PMID 22091368, 2010). "The bleeding diathesis is not due to impaired platelet function but rather to an acquired Von Willebrand's disease caused by proteolytic reduction of Von Willebrand Factor (VWF) multimers." (PMID 17210076, 2007). "•Type 2A von Willebrand disease leads to loss of large VWF multimers and bleeding." (PMID 41322113, 2025). "Deficiencies in VWF, whether quantitative or qualitative, lead to von Willebrand’s disease (VWD), the most common inherited bleeding disorder." (PMID 40116934, 2025). "Abnormalities in the VWF protein due to VWF mutations would result in von Willebrand disease (VWD), a common inherited bleeding disorder with an estimated prevalence from 1 per 1000 to 1 per 100 population, while the real prevalence is still not well established yet." (PMID 40529342, 2025). "Moreover, LSEC targeting overcomes a roadblock to gene therapy of von Willebrand disease caused by the inability of hepatocytes to multimerize von Willebrand factor protein, which is required for long-term functionality." (PMID 39881029, 2025). "Reduced or dysfunctional VWF is associated with bleeding, known as von Willebrand disease." (PMID 40789313, 2025). "Von Willebrand disease is caused by either a quantitative or qualitative defect in VWF secretion." (PMID 40362344, 2025). "Finally, a Likely Pathogenic variant, p.Ser1517Arg, was found in VWF (encoding von Willebrand factor), and has been reported in a patient with von Willebrand disease type 2 (OMIM #613554), underscoring the potential role of FAM20C in the coagulation pathway." (PMID 41301500, 2025). "Mutations in VWF cause von Willebrand disease, a hereditary bleeding disorder." (PMID 38825675, 2024). "Deficiencies of VWF, along with clinical bleeding symptoms, define von Willebrand disease." (PMID 38363768, 2024). "Inherited von Willebrand disease may, in addition, result in angiodysplasia via a mechanism related to loss of vWf in Weibel-Palade bodies." (PMID 38510715, 2024). "A deficiency or defect of VWF causes von Willebrand disease (VWD)." (PMID 38066509, 2023). "Deficiency or structural defects of VWF lead to Von Willebrand disease (VWD)." (PMID 35897115, 2022). "VWF deficiency can lead to von Willebrand disease and bleeding." (PMID 35136382, 2022). "However, as described in the previous section, quantitative (Types 1 and 3) and qualitative (Type 2) deficiencies of VWF occurs that result in von Willebrand disease (VWD), characterized by excessive mucocutaneous bleeding." (PMID 34575297, 2021). "High haemodynamic forces present in the systemic arterial system result in platelets binding to vWF through integrin αIIbβ3 for the initiation of aggregation, while patients with vWF deficiency as a result of von Willebrand disease are partly protected against arterial thrombosis." (PMID 33925795, 2021).
Von Willebrand disease (continued). "Von Willebrand disease (VWD) is a hereditary hemorrhagic disorder caused by a genetic defect with a mutation of the gene encoding the von Willebrand Factor (VWF), located on chromosome 12, which causes a quantitative, structural or functional fault, in the VWF." (PMID 32140581, 2020). "In addition, adsorption of high molecular weight multimers of von Willebrand factor (vWF) to platelet GPIbα leading to loss of large vWF multimers and acquired von Willebrand disease contributes to the bleeding diathesis." (PMID 31258539, 2019). "Von Willebrand’s disease (VWD) is an inherited haemorrhagic disease caused by a genetic defect that determines a quantitative structural or functional anomaly of the Willebrand factor (VWF)." (PMID 30999657, 2019). "Notably, the vWF gene variant c.4937A>G previously associated with von Willebrand’s disease (vWD) type II was present in many more breeds than currently acknowledged." (PMID 27525650, 2016). "Patients undergoing CF-LVADs insertion show features suggestive of acquired von Willebrand disease caused by deficiency or dysfunction of von Willebrand Factor (vWF), a key clotting protein whose interaction with platelets and vessel wall generates primary haemostasis." (PMID 29367578, 2016). "Von Willebrand disease (VWD) may be caused by an impaired von Willebrand factor (VWF) synthesis, its increased clearance or abnormal function, or combinations of these factors." (PMID 27532107, 2016). "Additionally, it is valuable to monitor this enzyme activity during von Willebrand Disease (VWD) type 2A since point mutations in the VWF A2-domain during this disease enhance VWF susceptibility to ADAMTS13-mediated proteolysis." (PMID 25992814, 2015). "Mutations in the VWF gene cause von Willebrand disease because of deficiency of vWF." (PMID 25646961, 2015). "Quantitative and/or qualitative deficiencies in secreted vWF multimers lead to the most common bleeding disorder in humans, von Willebrand’s disease, which is estimated to affect up to 1% of the population, while elevated serum vWF levels are associated with cardiovascular pathologies." (PMID 24794632, 2014). "An elevated plasma level of VWF is an independent risk factor for coronary heart disease (CHD), ischemic stroke, and peripheral artery disease, whereas low VWF antigen and activity could result in bleeding associated with von Willebrand disease (VWD)." (PMID 24465435, 2014). "Besides complete VWF deficiency, variable levels of macrothrombocytopenia identified in type 2B von Willebrand disease, a disorder characterized by gain-of-function mutations, point to a role of VWF in the regulation of platelet production." (PMID 23737952, 2013). "We recently described a new role for VWF in controlling angiogenesis, which may have significant clinical implications for patients with Von Willebrand disease (VWD), a genetic or acquired condition caused by the deficiency or dysfunction of VWF." (PMID 24106610, 2013). "Indeed, quantitative and/or qualitative abnormalities of VWF are associated with the bleeding disorder Von Willebrand disease (VWD)." (PMID 23936617, 2013). "VWF gene mutations cause the hemorrhagic von Willebrand disease (VWD)." (PMID 22479377, 2012). "VWF mutations cause von Willebrand disease, but incomplete penetrance is known." (PMID 21858020, 2011). "The in vitro study showed that vWF multimerized through sequential stacking steps is assembled as a right-hand helical tubular storage, and clinical mutations of vWF in disrupting the assembly may lead to von Willebrand disease." (PMID 40277561, 2025). "Additionally, vWF deficiency or dysfunctionis associated with von Willebrand disease." (PMID 39625149, 2024). "Indeed, a bleeding phenotype is a prerequisite for some diagnoses, such as the Bleeding Disorder of Unknown Cause and type 1 von Willebrand disease (VWD) with von Willebrand factor (VWF) levels between 30 and 50 International Units/dL." (PMID 36696194, 2023).
Von Willebrand disease (continued). "In addition, the premature loss of FVIII caused by the VWF deficiency may induce the dual defect in haemostasis in the patients with von Willebrand disease (VWD)." (PMID 36760352, 2023). "However, it may appear surprising that in type 3 von Willebrand disease patients (and in Vwf −/− mouse blood) with complete VWF deficiency, platelet counts and platelet size appear to be normal." (PMID 23737952, 2013). "Further, von Willebrand Disease (VWD), another bleeding diathesis, results from a quantitative or qualitative deficiency in von Willebrand factor (VWF), a critical component of primary hemostasis." (PMID 41509549, 2026). "Both had markedly prolonged activated partial thromboplastin time, reduced factor VIII, and severely diminished VWF activity and antigen levels, confirming the diagnosis of severe type 3 von Willebrand disease." (PMID 41988445, 2026). "Von Willebrand disease (VWD) is the most common inherited coagulopathy, resulting from a deficiency of von Willebrand factor (VWF), which plays a central role in hemostasis." (PMID 41988445, 2026). "We describe treatment outcomes and healthcare resource utilisation (HCRU) in adults with von Willebrand disease (VWD) treated on demand with recombinant von Willebrand factor (rVWF) in the United Kingdom." (PMID 41071579, 2026). "We describe treatment outcomes and healthcare resource utilisation (HCRU) in adults with von Willebrand disease (VWD) receiving recombinant von Willebrand factor (rVWF) in surgical settings in the United Kingdom." (PMID 41074914, 2026). "Von Willebrand disease (VWD) is a common inherited bleeding disorder caused by quantitative (Type 1 and Type 3) or qualitative (Type 2) defects in von Willebrand factor (VWF), which stabilises Factor VIII (FVIII) and supports platelet adhesion." (PMID 41085048, 2025). "Von Willebrand disease (VWD), the focus of the present case, is a hereditary bleeding disorder caused by quantitative or qualitative deficiencies in the clotting factor von Willebrand factor (VWF), leading to impaired coagulation and increased bleeding risk." (PMID 40546502, 2025). "In von Willebrand disease (VWD), 88.2% of patients had VWF mutations, including splice-site and nonsense variants linked to type 2 VWD, though vWF activity was not significantly different between groups." (PMID 40488813, 2025). "Type 1 von Willebrand disease (VWD) is often caused by variants in von Willebrand factor (VWF), including p.R1205H (“Vicenza mutation”), which accelerate VWF clearance via macrophage receptor LRP1 and impair platelet adhesion and activation." (PMID 41337046, 2025). "Based on the clinical presentation and examination, differential diagnosis includes clotting disorders such as von Willebrand disease and platelet function abnormalities, which were excluded by a normal coagulation profile and von Willebrand factor assay." (PMID 41025027, 2025). "Desmopressin (DDAVP) serves as a therapeutic agent in type 1 von Willebrand disease (vWD) by promoting the endogenous release of vWF from endothelial cell stores, thereby transiently augmenting plasma vWF and factor VIII levels." (PMID 40572775, 2025). "The development of inhibitors to von Willebrand factor (VWF) is a rare but potentially serious complication of VWF replacement therapy in patients with von Willebrand disease (VWD)." (PMID 40673043, 2025). "On the contrary, individuals with low VWF levels in plasma, such as patients experiencing the bleeding disorder von Willebrand disease, have shown to be protected of developing arterial thrombotic events." (PMID 40093962, 2025). "Laboratory evaluation revealed reduced von Willebrand factor activity, consistent with acquired von Willebrand disease, presumed secondary to extreme thrombocytosis resulting in shear-induced proteolysis of von Willebrand factor multimers." (PMID 41552126, 2025).